CD4 (CD4 molecule)
Diseases named in the same sentence as CD4 in open-access papers (continued):
Sharing a sentence is not in itself a finding about the gene and the disease.
ZIKV infection (73 papers, 2017 to 2026). "In a mouse model of ZIKV infection, the authors demonstrated that CD4+ deficiency reduces GC B cells, impairs LLPC formation, and leads to a rapid decline in neutralizing antibodies." (PMID 41295476, 2025). "Acute ZIKV infection was also associated with activation of T helper type 1 (Th1) and Tctl T cell CD4+ T cell subsets." (PMID 35584677, 2022). "In both the CD4 depleted and control mice we saw evidence of ZIKV infection and disease, which included weight loss, and temporary hind limb paralysis beginning day 7 post infection." (PMID 30212537, 2018). "Results obtained from this study indicate the potential of the Asian-lineage Zika Env-CD4 and Env proteins in ELISA assays to monitor humoral immune responses in upcoming clinical trials as well as a sero-diagnostic tool in ZIKV infection." (PMID 30587198, 2018). "Here the authors show roles for CD4+ T cells and the associated IFNγ signaling in antibody-mediated resistance to Zika virus infection." (PMID 30087337, 2018). "Although IFNAR deficient mice are known to be susceptible to ZIKV infection, depleting CD4 T cells from 10–12 week old IFNAR knock-out (KO) mice caused higher viral loads, more severe paralysis, and reduced survival, and caused lethal infection in 3-4 week old IFNAR KO mice." (PMID 31382545, 2019). "Third, we examined whether CD4+ T cells could contribute to protection against ZIKV infection in fully deficient Ifnar1−/− mice, which are more susceptible than LysMCre+Ifnar1fl/fl mice to ZIKV infection." (PMID 30677097, 2019). "In particular, ZIKV infection was associated to a reduction of IFN-γ production by CD4 T-cells." (PMID 28740159, 2017). "In rhesus macaques, depletion of CD4 T cells before DENV or ZIKV infection resulted in a significant increase in viremia, and an altered quality of the humoral immune response." (PMID 39418312, 2024). "In interferon α/β receptor-deficient HLA-DRB1*0101 transgenic mice, dengue and Zika virus cross-reactive CD4 Th1 cells were shown to be protective against ZIKV infection, in an antibody-independent manner." (PMID 39418312, 2024). "This is also supported by prior studies that showed CD4+ T-cell depletion during primary ZIKV infection negatively impacted the development of antibody responses in mice." (PMID 39388457, 2024). "Effector CD8 T cells and Th1 CD4 T cells are generated in response to ZIKV infection in the host and play important roles in restricting ZIKV replication when type I IFN response is compromised." (PMID 37112733, 2023). "Peripheral Blood Mononuclear Cells (PBMC) of individuals with previous ZIKV infection were tested for cytokine production in response to the pool of CD4 and CD8 ZIKV peptide selected." (PMID 34997041, 2022). "As this humoral response is dependent on CD4 + T cells, such cell population is also required for complete protection against ZIKV infection, specially Th1 cells." (PMID 34997041, 2022). "It has been reported that the ZIKV-specific CD4+ T cell response is critical for B cell activation and subsequent antibody maturation, playing a key role in resistance to primary ZIKV infection." (PMID 35615356, 2022). "In studying the immunological features of ten women with acute ZIKV infection, Tonnerree and coworkers revealed that CD4+T cells were shown to target capsid protein, pre-M protein, Envelop protein, NS1, NS3, and NS5 proteins." (PMID 35736984, 2022). "(2017), mouse models were used to investigate the response of CD8+ and CD4+ T cells to ZIKV infection." (PMID 36159640, 2022). "It has been reported that CD4+ T cells promote humoral immunity and viral control during Zika virus infection." (PMID 35463639, 2022). "During ZIKV infection, CD4+ T cells differentiate into Th1 cells able to produce IFN-γ, IL-2, TNF-α cytokines, and transcription factor T-bet." (PMID 35746638, 2022).
ZIKV infection (continued). "Anti-ZIKV vaccines are therefore focused on generating protective CD8+ and CD4+ T cells in order to control ZIKV infection and promote virus clearance, thereby avoiding harmful ADE effects with potential reinfection events by ZIKV or other flaviviruses." (PMID 33810028, 2021). "Overall, like DENV infection, our data indicate that the Temra CD4 T cell subset is enriched for responding IFN-γ-secreting CD4 T cells for ZIKV epitopes in donors with a history of ZIKV infection." (PMID 33679748, 2021). "CD4+ T cells were found to differentiate into Th1 cells during ZIKV infection as evidenced by the increased production of IFN-γ, IL-2 and TNF-α cytokines and transcription factor T-bet." (PMID 34745123, 2021). "Although the involvement of viral antigen specific CD4+ T cells in the control of ZIKV infection and disease is still controversial, the CD8+ T cell response is associated with the control of the ZIKV infection and pathogenesis." (PMID 33810028, 2021). "ZIKV infection elicited virus-specific IgG in the lumen of the vagina and recruited virus-specific T cells (CD4+ and CD8+ T cells) to the female reproductive tract (FRT)." (PMID 34745123, 2021). "Protective adaptive immunity to ZIKV has been mainly attributed to neutralizing antibodies but the role of cytotoxic CD8+ T cells, as well as CD4+ T cells and IFNγ signaling in antibody-mediated resistance to ZIKV infection has also been suggested." (PMID 32194996, 2020). "This suggests that previous DENV immune status preferentially shapes the CD4+ T cells effector responses to a ZIKV infection." (PMID 32463814, 2020). "The IFNγ response in the CD4+ T cells from the DENV 12M group before ZIKV infection is remarkable (left)." (PMID 32463814, 2020). "Here, we show that both monocytes and CD4+ T cells (LyT) showed an increase in binding to hBLECs under ZIKV infection conditions." (PMID 32753493, 2020). "In a cohort of 45 American patients with confirmed ZIKV infection, highly polyfunctional CD4 and CD8 T cells responses were detected following stimulation with pools of 15mer peptides (overlapping by 11 peptides) from all ZIKV proteins." (PMID 31382545, 2019). "Accordingly, Pardy and colleagues revealed that CD4+ T cells responding to ZIKV infection in wildtype mice were also predominantly of a Th1 phenotype, although the response to isolated ZIKV peptides was not investigated in this study." (PMID 30677097, 2019). "Although recent work has shown that ZIKV infection induces activation and expansion of CD4+ T cells with a Th1 phenotype, those studies did not analyze the antigen specificity of the response." (PMID 30677097, 2019). "In particular, one study identified capsid and envelope protein-specific CD4 T cell responses following ZIKV infection." (PMID 31382545, 2019). "To confirm and extend this result showing CD4+ T cell contribution to protection against IVag ZIKV infection in LysMCre+Ifnar1fl/fl mice, we depleted CD4+ T cells in Ifnar1−/− mice on days −3 and −1 before IVag infection with a lethal dose of ZIKV." (PMID 30677097, 2019). "Our results thus far reveal a mixed role for CD4+ T cells in promoting Ab and viral clearance to ZIKV infection via the RO route." (PMID 30677097, 2019). "In our study, we used peptide vaccination and adoptive transfer experiments to demonstrate that ZIKV-specific memory CD4+ T cells can promote viral clearance during RO ZIKV infection." (PMID 30677097, 2019). "In conclusion, our data provide evidence for qualitatively different protective roles of CD4+ T cells in ZIKV infection via the RO and IVag routes." (PMID 30677097, 2019). "To investigate the localized immune response to IVag ZIKV infection, we analyzed CD4+ T cell activation in the local (iliac) draining lymph nodes (LNs) on day 10 after infection." (PMID 30677097, 2019). "In another report, Winkler and colleagues detected proliferation of CD4+ T cells in response to ZIKV infection of wildtype mice." (PMID 30677097, 2019).
ZIKV infection (continued). "We have recently shown that a robust and polyfunctional CD4+ T cell response is elicited during ZIKV infection in mice." (PMID 31143185, 2019). "Among infected donors, we observed ZIKV infection in CD3+CD4+ T cells, CD3+CD8+ T Cells, CD3−CD19+ B cells and CD14+ monocytes, albeit the relative numbers of infected subpopulations varied among donors." (PMID 31752731, 2019). "CD4+T cells have been shown to be important for controlling some flavivirus infections, but a role for CD4+T cells during ZIKV infection is still unclear." (PMID 30212537, 2018). "In this work, we provide the first description of the epitope specificities in such CD4 T cell responses after ZIKV infection in humans and an analysis of the results in the context of the three-dimensional structures of the capsid and envelope proteins." (PMID 29899743, 2018). "To determine if CD4+T cells were protective against ZIKV infection we utilized the Ifnar1-/- mouse model of infection." (PMID 30212537, 2018). "In conclusion, our study demonstrate a critical role of CD4+ T cells, type 2 IFN receptor signaling, CD8+ T cells and B cells in the immune response and control of ZIKV infection in type 1 IFNR-deficient mice." (PMID 30087337, 2018). "Once we determined that CD4+T cells were protective, we performed a screen with an overlapping peptide library covering the ZIKV proteins and identified multiple epitopes that stimulated CD4+T cell responses during ZIKV infection." (PMID 30212537, 2018). "To determine if CD4+T cells were protecting the central nervous system (CNS) from ZIKV infection we measured viral titers in the 10–12 week-old CD4 depleted and control mice at different times post infection." (PMID 30212537, 2018). "In our patient, more than 50% of the CD4+CD8dim T cells during acute ZIKV infection were CD45RA+CD226+CR-." (PMID 30596671, 2018). "Overall CD4 T cell responses to the ZIKV structural proteins were determined by IL-2 ELISPOT assays using PBMCs from 14 patients with laboratory-confirmed ZIKV infection and peptide pools of C, prM, and E." (PMID 29899743, 2018). "Reports have identified the presence of CD4+T cells during ZIKV infection but their function during the course of infection has yet to be determined." (PMID 30212537, 2018). "Overall these data demonstrate that generating polyfunctional and polyclonal CD4+T cell responses are important correlates for protection during ZIKV infection." (PMID 30212537, 2018). "We determined the TCR V-β sequences within the antigen specific CD4+T cells isolated during acute ZIKV infection." (PMID 30212537, 2018). "As both CD4+ and CD8+ T cells were shown to contribute to protection against DENV infection, a comprehensive analysis of MHC class II-restricted response is needed to determine the role of CD4 in ZIKV infection and disease protection." (PMID 30205518, 2018). "Thirty days after ZIKV infection we saw a strong polyfunctional CD4+ T-cell response, where the CD4+ T cells from BS14 made IFN-γ (0.70%), TNF-α (9.6%) and CD107a (2%) in response to the E peptide pool stimulation." (PMID 28643775, 2017). "During ZIKV infection, a CD4 T-cells differentiation towards effectors was described, suggesting the induction of a well coordinate immune response." (PMID 28740159, 2017). "The immunodominant epitopes vary between DENV and ZIKV infection and between CD4+ and CD8+ T cells." (PMID 39418312, 2024). "Thus far, all published studies agree that, especially in the acute phase of ZIKV infection, an environment favorable to the activation and differentiation of naive CD4+ T cells into Th17 cells exists." (PMID 35215843, 2022). "Specifically, in ZIKV infection, these activated CD4+ T cells could further differentiate into effector memory and terminally differentiated T cells, enhancing the production and acquisition of cytokines." (PMID 35215836, 2022).
ZIKV infection (continued). "Acute ZIKV infection was also associated with a transient increase in the abundance of small sub-populations of cycling and activated non-naïve CD4+ T cell subsets and cytotoxic-skewed γδ T cells." (PMID 35584677, 2022). "Apart from binding affinity and promiscuity, we also considered IFN-γ induction capability in order to select our vaccine’s CD4 + T cell peptides, since high levels of this cytokine during the acute phase of ZIKV infection appears to be related to viral clearance and mild disease." (PMID 34997041, 2022). "However, it has also been suggested that T cells are dispensable for ZIKV infection, as depletion of both CD4 and CD8 T cells prior to infection with a Brazilian ZIKV isolate led to only a small but significant weight loss compared to control-treated mice." (PMID 34193875, 2021). "However, the involvement of viral antigen specific CD4+ T cells in the control of ZIKV infection and disease is still controversial." (PMID 33810028, 2021). "Our work builds on these observations and demonstrates that DENV specific CD4+ T cells isolated one year after DENV infection were highly responsive to the whole DENV virus prior to ZIKV infection (characterized by a significantly higher frequency of IFN-γ production or CD107a expression)." (PMID 32463814, 2020). "Our results are in agreement with this, showing a significant increase of circulating perforin by day 7 p.i. correlating with a higher expression of CD107a and higher frequency of IFN-γ production on CD4+ T cells in animals exposed to DENV 12 months before ZIKV infection." (PMID 32463814, 2020). "ZIKV infection resulted in the attenuation of the inhibitory capacity of CD4+CD25+ T cells." (PMID 32057179, 2020). "Thus, IVag ZIKV infection induced a vigorous Th1 CD4+ T cell response in the spleen and draining LNs comparable to that observed in the spleen after RO infection." (PMID 30677097, 2019). "We next asked whether CD4+ T cells are required for the primary CD8+ T cell response to ZIKV infection, as we have previously demonstrated a critical role for CD8+ T cells in protecting against primary ZIKV infection." (PMID 30677097, 2019). "In this study, we investigated the role of CD4+ T cells in the response to primary ZIKV infection via systemic (intravenous) and sexually transmitted (intravaginal) routes using LysMCre+Ifnar1fl/fl and Ifnar1-/- C57BL/6 mice for investigation of the CD8+ T cell response to ZIKV." (PMID 30677097, 2019). "To determine whether this was also the case for the primary response to IVag infection, we performed a similar analysis using progesterone-pretreated LysMCre+Ifnar1fl/fl mice that were infused with a control or depleting anti-CD4 Ab before IVag ZIKV infection." (PMID 30677097, 2019). "Notably, we also observed the same pattern of expansion of CD4+ T cell subsets in the spleen on day 10 after IVag ZIKV infection as we had on day 7 after RO infection." (PMID 30677097, 2019). "Second, we asked whether memory CD4+ T cells contribute to viral clearance during secondary ZIKV infection." (PMID 30677097, 2019). "Hematology on CD4+T cell depleted or control Ifnar1-/- mice following ZIKV infection." (PMID 30212537, 2018). "Studies investigating the T cell response for ZIKV in both humans and mice have identified a role for CD4+T cells in responding to ZIKV infection although their importance and sufficiency in the protection against ZIKV morbidity and mortality has not been clearly defined." (PMID 30212537, 2018). "Moreover, serum obtained after 7 days of ZIKV infection from AG129 mice or from mice depleted of CD4+ T cells had significant lower titers of anti-ZIKV IgM, IgG and IgG2a isotype compared to serum from A129-infected mice." (PMID 30087337, 2018). "We also observed a partially protective role for CD4+ T cells in this study, suggesting that CD4+ T cell-mediated-help may shape an optimal cross-reactive CD8+ T cell response during ZIKV infection of DENV-immune pregnant females." (PMID 30072692, 2018).
ZIKV infection (continued). "Endpoint reciprocal titers showed that all patients with previous ZIKV infection have high mean titer of 3.84 and Z12 had the highest titer of 5.34 using Env-CD4 whilst commercial Env showed a significantly lower mean titer of 3.16 and Z12 had the titer of 4.38." (PMID 30587198, 2018). "It should also be noted that many previous studies evaluating the importance and implications of TCR diversity on the immune response were completed with CD8+T cells, leaving open the question of the impact of TCR diversity in CD4+T cells in controlling ZIKV infection." (PMID 30212537, 2018). "Notably, CD4+ T cell and B cell responses and IFNγ signaling were fundamental to protection against primary ZIKV infection." (PMID 30087337, 2018). "On day eight post ZIKV infection we harvested the brains of four CD4 depleted and control mice." (PMID 30212537, 2018). "Overall this study identifies a novel role for polyfunctional and polyclonal CD4+T cells in providing protection against ZIKV infection and highlights the need for vaccines to develop robust CD4+T cell responses to prevent ZIKV neuroinvasion and limit replication within the CNS." (PMID 30212537, 2018). "The Th1 cells induced by ZIKV infection also exhibited a high degree of poly-functionality (multiple cytokine production), as over 65% of responding CD11a+CD49d+ CD4+ T cells were IFN-γ+TNF-α+ double-producers, and over 60% were IFN-γ+TNF-α+IL-2+ triple-producers." (PMID 28231312, 2017). "During ZIKV infection, CD4+ helper T-cells promote the development of nAb responses, perform cytotoxic functions and direct the immune response through cytokine-secretion, and may potentially protect against nervous tissue damage or provide limited protection during pregnancy." (PMID 39388457, 2024). "The results indicate that the ZIKV peptides of our in silico designed vaccine were presented to T cells in the course of natural ZIKV infection and generated memory responses that could be boosted by peptide stimulation in vitro leading to cytokine production by CD4 + and CD8 + T cells." (PMID 34997041, 2022). "CD4 + T cell differentiation into effector memory and terminally differentiated cells was observed in patients in the acute phase of ZIKV infection 48, which suggests that a CD4 + T cell epitope-based vaccine may contribute to eliciting a cytokine inducing response." (PMID 34997041, 2022). "Whether ZIKV CD4 + T cell responses are necessary for virus clearance in primary infection is still controversial, but memory CD4 + T cells elicited by infection or peptide immunization have been demonstrated to protect host from subsequent ZIKV infection." (PMID 32265852, 2020). "Moreover, it has been observed in multiple studies in humans, NHPs, and mice that DENV immunity does modulate the cellular immune response to ZIKV—specifically that prior immunity to DENV leads to more robust CD8+ and CD4+ T cell responses during ZIKV infection." (PMID 31143185, 2019). "Thus, provision of help for Ab responses may be a dominant feature of the protective role of CD4+ T cells during primary ZIKV infection." (PMID 30677097, 2019). "Knowing that CD4+T cells were required for control of ZIKV infection and that we could detect a strong antigen specific CD4+T cell response in the mice, we hypothesized that the TCR repertoire specific for the different CD4 epitopes would contain a high degree of diversity." (PMID 30212537, 2018). "Therefore, we hypothesized that the consequences of CD4+ T cell depletion during ZIKV infection would be difficult to detect in 4-week-old Ifnar1-/- mice." (PMID 30212537, 2018). "When examining the relative proportions of CD4+ and CD8+ in the activated T-cell compartment, acute DENV and ZIKV infection were predominantly CD8+." (PMID 41346606, 2025). "ZIKV infection stimulates the infiltration of multiple immune cell types into CNS tumours, including CD8+ and CD4 + T cells, which contribute to ZIKV-induced tumour clearance." (PMID 41166287, 2025).